ACSS2 (acyl-CoA synthetase short chain family member 2)
Diseases named in the same sentence as ACSS2 in open-access papers (continued):
Sharing a sentence is not in itself a finding about the gene and the disease.
tumor (continued). "Furthermore, it has been reported that a significant proportion of ACSS2 localizes to the nuclei of tumor cells, and how much exogenous acetate can contribute to nuclear processes such as histone acetylation remains unknown." (PMID 28099844, 2017). "Moreover, inhibiting acetate assimilation by targeting acetyl-CoA synthetases (e.g., ACSS2) may impair tumor growth." (PMID 25671109, 2014). "Simultaneously, in two groups of xenograft tumor mouse models established using NC CAL27 cells, we observed that the administration of ACSS2 inhibitors markedly suppressed tumor growth, while exerting no significant impact on the body weights of the mice." (PMID 40858538, 2025). "This study aimed to further explore the role of ACSS2 and TFEB in HNSCC and how they affect the biological behavior of tumor cells by regulating autophagy." (PMID 40858538, 2025). "The inhibition of acetyl-CoA synthetase (ACSS2) and long-chain acyl-CoA synthetase 4 (ACSL4) has resulted in a marked decrease in tumour growth and therapeutic sensitivity in various cancers." (PMID 38610991, 2024). "The critical enzymes for synthesizing acetyl-CoA, including adenosine triphosphate (ATP)-citrate lyase (ACLY), acetyl-CoA synthetase 1 (ACSS1), and acetyl-CoA synthetase 2 (ACSS2), are observed to have important effects in promoting tumor progression." (PMID 37122003, 2023). "Phosphorylation at Ser267 of ACSS2 by CDK5 kinase inhibits the degradation of ACSS2 and promotes the growth of GBM tumor cells." (PMID 37143582, 2023). "Acyl-CoA synthetase short-chain family member 2(ACSS2) is a vital enzyme in cancer metabolism, which during stress conditions, supplies tumor cells with Acetyl-CoA by taking up acetate as a carbon source." (PMID 38260844, 2023). "Phosphorylation at Ser267 of ACSS2 by CDK5 inhibits the degradation of ACSS2 and promote the growth of GBM tumor cells." (PMID 37143582, 2023). "Acss2 regulates dynamic HIF-2α acetylation, Cbp/HIF-2α complex formation, Cbp/HIF-2 signaling, and tumor cell growth and metastasis." (PMID 36862715, 2023). "We selected two enzymes of fatty acid metabolism for further investigation, namely, ACSS2 and FASN, which are emerging markers of tumour metabolism." (PMID 36010906, 2022). "It was found that the acetylation of HIF-2α in the presence of ACSS2 significantly increased the expression level of HIF-2α target gene and promoted the growth of tumor cell lines in vitro." (PMID 35740562, 2022). "For each patient sample block, two tumor tissue spots and one normal control spot were used for TMA; IHC analysis of ACSS2 and PDL1 was used as an example." (PMID 34206705, 2021). "In response to chronic stimulation by tumor antigens, exhausted CAF continue to activate the expression of ACSS2 and other immune checkpoint receptors, which further promotes tumor invasion." (PMID 34206705, 2021). "In contrast, patients with low tumor expression of both KHK-A and ACSS2 pS659 had the best prognosis with the highest OS rate (5-years OS: 69.1%)." (PMID 31750240, 2019). "In this study, we show that Acss2 regulates dynamic HIF-2α acetylation, Cbp/HIF-2α complex formation, Cbp/HIF-2 signaling, epigenetic remodeling, and tumor cell growth and metastasis." (PMID 29281714, 2017). "Overall, ACSS2 staining was particularly intense in hypoxic (high CAIX, low CD31) regions of the tumor and exhibited prominent nuclear localization." (PMID 28099844, 2017). "KRAS G12D tumor growth was significantly inhibited by trametinib and by the ACSS2 inhibitor, although the combination of the two did not add any benefit." (PMID 40131933, 2025). "The ACSS2/KAT2 A complex is formed in response to EGFR activation by ERK phosphorylation-mediated nuclear translocation of ACSS2, which acts as a lactyltransferase to enhance histone lactylation, gene expression, tumor development, and immune evasion." (PMID 40295451, 2025).
tumor (continued). "Moreover, ACSS2 also upregulates the expression of the autophagy-related factor LAMP1 to promote autophagy, migration, and invasion in tumor cells." (PMID 41551149, 2025). "To validate the critical role of ACSS2 in PDAC baseline tumours without CAFs, we assessed the growth of orthotopic tumours depleted for ACSS2 in the in vivo model without CAFs and let the tumours grow longer until the mice reached the euthanasia criteria." (PMID 38429478, 2024). "In the G12D tumors, tumor growth was significantly inhibited by trametinib and an ACSS2 inhibitor, although combination of the two did not add any benefit." (PMID 38464238, 2024). "Remarkably, the KrasWT/G12V Acss2 KO cells were not able to proliferate despite initial tumor formation without ACSS2." (PMID 38464238, 2024). "Hypoxia and lipid metabolism-related gene acetyl-CoA synthetase 2 (ACSS2) is involved in tumor progression, but its role in pNENs is not revealed." (PMID 38263056, 2024). "We observed a significant reduction in the growth of tumours without CAF co-implantation when ACSS2 was knocked down in cancer cells, compared to the scrambled control tumours." (PMID 38429478, 2024). "Like ACLY, enforced expression of ACSS2 in T cells increased acetate-derived carbon incorporation in citrate and fatty acid, whereas reducing ACSS expression in T cells impairs IFN-γ production by tumor-infiltrating lymphocytes and tumor clearance." (PMID 38060103, 2023). "Moreover, the acetylation of HIF-2α in the presence of ACSS2 significantly increased the expression level of HIF-2α target genes, potentially linking tumor cell growth and metastasis." (PMID 38060103, 2023). "A closer examination of ACSS2’s downstream genes revealed that it enhances macropinocytosis through the downstream ETV4/ZIP4 pathway, while ZIP4 promotes cachexia via the GSK3βB/TRAIL axis, ultimately resulting in tumor cachexia." (PMID 37720505, 2023). "We further documented that astrocytic tumours of different grades showed a corresponding increase in nuclear sXBP1 and ACSS2 localisation in acidified regions, indicating the preservation of GM3‐sXBP1‐ACSS2‐Cholesterol survival machinery in acidified tumour zones." (PMID 34811795, 2022). "Research on ACSS2 in tumors is gradually increasing, and the identified effects of ACSS2 on the biological characteristics of tumor cells are not completely consistent." (PMID 35798917, 2022). "In addition, the expression levels of KHK-A and ACSS2 pS659 were significantly higher in NSCLC tissues than those in adjacent non-tumor tissues, indicating that NSCLC specimens have increased KHK-A and ACSS2 pS659 expression levels." (PMID 31750240, 2019). "We reasoned that tumor growth and metastasis depends upon Acss2 signaling in the nucleus rather than Acss2 cytosolic lipid synthesis." (PMID 29281714, 2017). "Primary tumor weight and luciferase activity as well as metastatic lung luciferase activity are similar in mice with control shRNA knockdown, WT Acss2 knockdown/rescue, or SV40-CYT Acss2 knockdown/rescue flank tumors." (PMID 29281714, 2017). "Tumor burden measured by weight or luciferase activity were substantially reduced for ACSS2 and HIF-2α depleted cells, but not for control or HIF-1α depleted cells." (PMID 25689462, 2015). "Other reports concluded that ACSS2 has no major role in lipid biosynthesis in glycolytically active [18F]FDG-avid tumor cells based on the observation of low [11C]acetate accumulation." (PMID 22886728, 2013). "Remarkably, KRAS G12V; ACSS2 KO cells were not able to proliferate despite initial tumor formation." (PMID 40131933, 2025). "In addition, in mice with tumor formation in situ, the tumor bodies of the group with high expression of PPARG also had higher expression levels of genes related to fatty acid metabolism, such as ACACA, ACLY and ACSS2 and so on." (PMID 40303293, 2025). "Lacking ACSS2 attenuates tumor burden without any phenotypic defects." (PMID 37164974, 2023).
tumor (continued). "However, in the high ACSS2 group, the phenotype of TME tended to be immunosuppressive, while the infiltrated CAF tended to be exhausted, synergizing with Tregs and ultimately leading to tumor metastasis and progression." (PMID 34206705, 2021). "These could help to identify new markers beside mTOR activity characterisation—such as FASN, CPT1a, ACSS2—or find good mitochondrial function markers (e.g. TOM20, NRF1), and to assign the metabolic expression profile of tumours before starting treatments in patients." (PMID 30574020, 2018). "We asked whether ACSS2 and HIF signaling affect tumor cell growth and metastases." (PMID 25689462, 2015). "Thus, acetate is capable of augmenting tumor growth in an ACSS2 as well as HIF-2, but not HIF-1, dependent manner, consistent with the specific effects of acetate on ACSS2/HIF-2 function at the molecular, biochemical, and cellular level." (PMID 25689462, 2015). "The opposite results in the same tumor, could it be that binding to rapamycin prevents it from working or decelerates its degradation, or again, that the selected cell line is not highly expressing ACSS2, looking forward to further exploration." (PMID 35740562, 2022). "Further, IHC scoring showed that the expression of ACLY, ACSS2, and PDH was higher in tumor tissues than in adjacent normal tissues, and there was no linear correlation between the expression level of ACLY, ACSS1, ACSS2, and PDH." (PMID 40791180, 2025). "Tumor burden and metastases increased with acetate supplementation for control or HIF-1α, but not ACSS2 or HIF-2α, knockdown." (PMID 25689462, 2015).
cancer (108 papers, 2013 to 2026). A tumor composed of atypical neoplastic, often pleomorphic cells that invade other tissues. "As a potential target for cancer therapy, ACSS2 is tightly associated to the cancer stage and patients' survival rate." (PMID 39584783, 2024). "Acetyl-CoA synthetase 2 (ACSS2)-dependent acetate usage has generally been associated with tumorigenesis and increased malignancy in cancers under nutrient-depleted conditions." (PMID 38528124, 2024). "ACSS2 has been implicated in numerous pathophysiological conditions, including inflammation, metabolic disorders, and cancer." (PMID 38515158, 2024). "The researchers discovered that high ACSS2 levels are linked with anabolic characteristics, reduced glycolysis, and lower hypoxia, which all point to less severe cancer." (PMID 38528124, 2024). "The elevation of lipogenic enzymes, including ATP-citrate lyase (ACLY) and acetyl-CoA synthetase 2 (ACSS2), resulted in increased fatty acid synthesis and is often associated with poorer prognosis in cancer patients." (PMID 36677015, 2023). "ACSS1 was associated with iHCC3, which had the lowest survival rate, whereas ACSS2 was associated with the moderate survival rate cancers (iHCC2) and ACSS3 was associated with the subtype having the longest patient survival rate (iHCC1)." (PMID 33304273, 2020). "Reconciling these discrepancies will be critical for understanding the actions associated with ACSS2 in cancer cells." (PMID 33304273, 2020). "NAA has been associated with the metabolic reprograming of cancer cells, where ACSS2 also plays a role." (PMID 33304273, 2020). "In the acetate metabolism, the gene-encoded acyl-CoA synthetase short-chain family member 2 (ACSS2) was downregulated in 5 cancer types." (PMID 31828117, 2019). "Surprisingly, HS-5 ACSS2-KO cells had a greater proliferative potential relative to wild type cells implicating a loss of ACSS2 could change proliferative rates in non-cancer cells." (PMID 38851813, 2024). "Future research on the underlying mechanisms whereby Acss2 acts to institute various metabolic programs in different organ systems will shed light on the pathophysiology of diseases ranging from metabolic disorder to cancer." (PMID 36835088, 2023). "A recent study has pointed out that cancer cells up-regulate ACSS2, which may cause by responding to stresses such as low nutrient availability and hypoxia." (PMID 36119478, 2022). "However, decreased ACSS2 expression has also been associated with increased rates of metastasis and poor prognosis in some cancer patients." (PMID 33917812, 2021). "Both ACSS1 and ACSS2 have been implicated in acetate utilization by cancer cells." (PMID 33304273, 2020). "Together, these findings demonstrate that the conversion of crotonate to crotonyl-CoA by ACSS2 is essential for the suppressive effect of crotonate on cancer cell migration." (PMID 41544165, 2026). "Depletion/reduction of ACSS2 has been reported to impair the growth of multiple cancer types, including breast, prostate, liver and glioblastomas." (PMID 41306968, 2025). "Research has shown that cancer cell lines show a significantly higher expression of the ACSS2 gene in their cytoplasm compared to normal cells, while the expression of ACSS1 in mitochondria remains unchanged." (PMID 41300803, 2025). "Previous studies have concentrated on ACSS2, which is upregulated in cancer cells under stress conditions, such as nutrient deprivation and hypoxia." (PMID 41306968, 2025). "Targeting FA synthesis by inhibiting FASN, ACLY, and ACSS2 has been the subject of numerous preclinical and several clinical studies in various cancers, including breast, lung, colon, prostate, and bladder." (PMID 40723225, 2025). "As such, the primary human ACS, ACSS2, has emerged as a cancer chemotherapy target and one ACSS2 inhibitor progressing to early-stage clinical trials." (PMID 39801522, 2025).
cancer (continued). "ACSS2 facilitates the formation of acetyl-CoA from acetate, providing the primary acetyl-CoA source necessary for synthesizing de novo fatty acids in cancer cells." (PMID 41300803, 2025). "Compared with normal cells, cancer cells exhibit an elevated uptake of carbon-14 labeled acetate, with ACSS2 being the prime gene responsible for promoting the conversion of carbon-14 labeled acetate into acetyl-CoA." (PMID 41300803, 2025). "Studies have demonstrated the link between metabolic stress and ACSS2 overexpression in many cancers; hence, it has attracted attention as a novel anticancer therapeutic." (PMID 40287570, 2025). "Studies have indicated that inhibitors targeting ACSS2 can effectively impede cancer development and, when combined with other antineoplastic drugs, mitigate treatment resistance." (PMID 39351241, 2024). "ACSS2 is often upregulated in various cancers along with altered expression of HATs, HDACs and associated epigenetic reader proteins." (PMID 38337680, 2024). "Our studies provide evidence for a role of ACSS2 and acetate in regulating polyamine levels in cancer cells via transcriptional reprogramming." (PMID 38429478, 2024). "Acetyl-CoA synthetase 2 (ACSS2), one of the enzymes that catalyze the conversion of acetate to acetyl-CoA, has been proved to be an oncogene in various cancers." (PMID 38887280, 2024). "Acetate usage depends on acetyl-CoA synthetase 2 (ACSS2); specifically, the use of acetate in cancers seems to occur mostly under nutrient-depleted or hypoxic conditions." (PMID 38528124, 2024). "Higher levels of certain enzymes, such as ATP-citrate lyase (ACLY), ACSS1, and ACSS2, have been observed in certain cancer types, promoting tumor growth and metastasis by providing an alternative energy source to glucose." (PMID 39456967, 2024). "The observed increase in Sox2 stability and expression upon modulation of Sox2 acetylation by ACSS2 inhibitor in both normal and cancer in vitro models underscores the significance of our study." (PMID 38473392, 2024). "These first-in-class BBB-permeable ACSS2 inhibitor analogs provide scaffolds for further optimization of ACSS2-targeting chemotypes and enable improved cancer treatments in the brain." (PMID 38818373, 2024). "ACSS2 is upregulated in various cancers, and increased levels of H3K9ac and H3K27ac have been observed in cancer cells." (PMID 38337680, 2024). "We further show that acetyl-CoA synthetase short-chain family member 2 (ACSS2) channels the exogenous acetate to regulate the dynamic cancer epigenome and transcriptome, thereby facilitating cancer cell survival in an acidic microenvironment." (PMID 38429478, 2024). "Cancer cells utilize acetate as a nutritional source in an ACSS2-dependent manner, supporting the biosynthesis of membrane phospholipids." (PMID 38990147, 2024). "For example, acetyl coenzyme A (CoA) synthetase 1 (ACSS1) and acetyl CoA synthetase 2 (ACSS2) have been shown to play a role in regulating how cancer cells utilize acetate, enhancing their ability to use acetate as an additional nutrition source." (PMID 39519507, 2024). "Acetate metabolism through ACSS2 seems to be important in leukemogenesis, although blood cancer cells are exposed to nutrient- and oxygen-rich environments." (PMID 38528124, 2024). "The inhibition of ACLY can be bypassed in some cancer cells and in the livers of mice fed a high-fructose diet through the upregulation of ACSS2." (PMID 37958642, 2023). "Preclinical studies have shown that ACSS2 can use acetate to mediate histone acetylation, which plays a key role in regulating gene expression, cell growth, and cancer development." (PMID 36707625, 2023). "To evaluate potential alternative acetyl-CoA–producing pathways, we generated cancer cell lines in which Acly and Acss2 are genetically deleted individually or in combination." (PMID 37134161, 2023). "HT1080 cancer cells exposed to oxygen or glucose deprivation generate acetate, which stimulates Acss2 nuclear translocation." (PMID 36862715, 2023).